POSTN (periostin)
Diseases named in the same sentence as POSTN in open-access papers (continued):
Sharing a sentence is not in itself a finding about the gene and the disease.
non-small cell lung carcinoma (26 papers, 2011 to 2026). A group of at least three distinct histological types of lung cancer, including non-small cell squamous cell carcinoma, adenocarcinoma, and large cell carcinoma. "POSTN + cancer-associated fibroblasts are associated with immune suppression and poor prognosis in non-small cell lung cancer." (PMID 39981232, 2025). "The involvement of periostin (POSTN) in non-small-cell lung cancer (NSCLC) migration, invasion, and its underlying mechanisms has not been well established." (PMID 35163164, 2022). "It is suggested that POSTN serum levels can be considered diagnostic and prognostic markers in patients with non-small cell lung cancer." (PMID 36077762, 2022). "The aim of this study was to determine periostin (POSTN) expression by cancer-associated fibroblasts (CAFs) in non-small-cell lung cancer (NSCLC), as well as to assess associations with clinicopathological factors and prognosis." (PMID 32987711, 2020). "Subsequently, analysis of the Cancer Cell Line Encyclopedia database indicated higher relative protein levels of POSTN in SCLC cell lines compared to non-small cell lung cancer (NSCLC) cell lines." (PMID 39762921, 2025). "Studies have reported the effect of POSTN expression on the prognosis of non-small cell lung cancer." (PMID 35832544, 2022). "POSTN is up-regulated in a wide variety of cancer, such as colon, pancreatic, breast, head and neck, thyroid, and gastric cancer, non-small cell lung cancer and neuroblastoma." (PMID 26716408, 2016). "In non-small-cell lung cancer, periostin expression also correlates well with lymphatic microvessel density." (PMID 22952986, 2012). "Periostin promotes the survival of endothelial cells and angiogenesis in certain types of cancer and angiogenesis and lymphangiogenesis have been observed to correlate with periostin in non-small cell lung cancer." (PMID 25369801, 2015). "Additionally, periostin is upregulated in response to the stress of hypoxia in the human A549 non-small cell lung cancer cell line and in rat pulmonary arterial smooth muscle cells (PASMCs)." (PMID 26023718, 2015). "POSTN is a soluble ECM protein and it is up-regulated in many cancers such as ESCA, head and neck squamous cell carcinoma, and non-small cell lung cancer." (PMID 33543230, 2021). "We classified 189 clinical specimens from patients with non-small cell lung-cancer according to high or low periostin expression, and found a better prognosis for patients with low rather than high periostin, even in cases of advanced-stage cancer." (PMID 30131847, 2018). "We here demonstrate that periostin is a negative prognostic factor that increases tumor proliferation through ERK signaling in non-small cell lung carcinoma." (PMID 30131847, 2018). "The present study aimed to detect the expression of periostin in the tissues of non-small cell lung cancer (NSCLC) patients and benign lung tumors, and to correlate the results with the clinicopathological data of the subjects, in order to evaluate periostin as a potential prognostic marker." (PMID 24273600, 2013). "In non-small cell lung cancer (NSCLC), POSTN has been found in mesenchymal areas in tumor stroma, but not in the cancer epithelial cells themselves." (PMID 29946533, 2018).
allergic disease (25 papers, 2012 to 2025). An immune response that occurs following re-exposure to an innocuous antigen, and that requires the presence of existing antibodies against that antigen. "A variety of different allergic diseases, such as bronchial asthma and AD, are associated with periostin expression." (PMID 39301836, 2025). "Periostin has been implicated in the pathogenesis of allergic diseases, such as asthma and atopic dermatitis." (PMID 38681405, 2024). "Next, we evaluated the levels of periostin associated with epithelial thickness and goblet cell hyperplasia in allergic diseases." (PMID 36421442, 2022). "In the context of spaceflight, astronauts with lower baseline periostin levels and a reduced propensity for periostin upregulation in response to inflammatory stimuli may be less susceptible to developing allergic reactions during long-duration space missions." (PMID 38681405, 2024). "Periostin has been linked to allergy and inflammation in a variety of different organs." (PMID 34512647, 2021). "Periostin has recently emerged as a promising biomarker of type 2 inflammation in allergic diseases, notably induced by signature type 2 cytokines like IL-4 and IL-13 or exacerbating their effects, thereby propagating allergic skin inflammation." (PMID 39722037, 2024). "POSTN has been intensively studied and clinically used as a biomarker, particularly for inflammatory and allergic diseases." (PMID 38020106, 2023). "Periostin has potential to become a novel prognostic biomarker and treatment target for many diseases including chronic fibrosis, inflammation, allergy and cancer." (PMID 35707463, 2022). "In allergic reactions periostin is involved in type 2 immunity and can be induced by IL-4 and IL-13 in bronchial cells." (PMID 34512647, 2021). "Among them, periostin (osteoblast-specific factor 2), like eosinophils, is an important regulator of the Th2 inflammatory response in individuals with allergic diseases." (PMID 34681210, 2021). "This review will discuss potential functions of periostin and its different isoforms in allergy and inflammation." (PMID 34512647, 2021). "Originally named osteoblast-specific factor 2, periostin is an extracellular matrix protein and, along with eosinophils, is a biomarker of Th2 inflammation in allergic diseases." (PMID 34681210, 2021). "Noteworthily, in an investigation on peripheral nerves, periostin was shown to chemotactically attract macrophages to the site of allergic reactions." (PMID 34512647, 2021). "That is why the patients with chronic inflammatory diseases, allergies, and acute infections were excluded from the analysis to avoid the impact of these comorbidities on the periostin level." (PMID 34063373, 2021). "In this review, we will discuss the function of periostin in allergy and inflammation, specifically taking into account the isoforms identified so far." (PMID 34512647, 2021). "This protein is an emerging biomarker reflecting type 2 inflammation in allergic diseases in humans, and it has also been suggested that periostin mediates intestinal inflammation in mice and promote tumorigenesis in humans." (PMID 31887112, 2019). "Since periostin—another novel biomarker for allergic diseases—is found at high levels in infants and children, SCC2 has a superiority as a biomarker for them, compared with periostin." (PMID 29642409, 2018). "The tests were performed on 63 patients (24 women and 39 men) with chronic rhinosinusitis and polyps (CRSwP—study group I), with determination of the COX-2, POSTN and IL-4 gene expression; an allergy was diagnosed in 38 cases." (PMID 25573836, 2015). "The high expression of the POSTN gene in patients with ChRS with Ps was related to the presence of an allergy." (PMID 25573836, 2015). "POSTN is a matricellular protein that plays a vital role in allergic disease development." (PMID 38020106, 2023).
allergic disease (continued). "Markers related to general inflammation or allergies such as C-reactive protein, serum lactate dehydrogenase, periostin, and peripheral eosinophil counts may be included as biomarkers correlated with clinical severity of AD." (PMID 36362483, 2022). "For instance, POSTN has emerged as a novel biomarker for type 2 inflammation in allergic diseases." (PMID 34513869, 2021). "POSTN has been intensively studied as a biomarker for inflammatory and allergic diseases." (PMID 34513869, 2021). "In other words, if the serum periostin level is high, it is expected to be a false positive due to the possibility of not being able to identify which fibrosis disease the subject is suffering from or due to a history of allergic disease." (PMID 34439751, 2021). "Periostin has been considered a promising biomarker in allergic disease." (PMID 33218117, 2020). "Moreover, recent studies have suggested that periostin facilitates the infiltration of neutrophils, as the first cells recruited to the site of an allergic reaction in the airway." (PMID 29854742, 2018). "Correspondingly, a protective role for periostin and TGF-β has been demonstrated in IgE-mediated allergies and airway hyperresponsiveness." (PMID 25981515, 2015).
renal fibrosis (24 papers, 2017 to 2026). A final common manifestation of a wide variety of chronic kidney diseases characterized by glomerulosclerosis and tubulointerstitial fibrosis. "After a unilateral ureteral obstruction, the renal periostin expression is upregulated and a periostin deficiency ameliorates renal fibrosis." (PMID 36009051, 2022). "Among the genes predicted to be regulated by p300 in proximal tubule cells during renal fibrosis, we selected the POSTN, FSTL1, and FSCN1 genes, as these encode secreted proteins that mediate interactions with surrounding cells and affect the mesenchymal transition." (PMID 40588562, 2025). "First, to investigate whether periostin was associated with TGF-β1-induced renal fibrosis, the expression of periostin was evaluated in cultured IMCD cells treated with or without TGF-β1." (PMID 28819200, 2017). "In addition to the vasculature, periostin has been linked to renal fibrosis in CKD." (PMID 36009051, 2022). "ATAC-sequencing analysis of PTCs from an ischemia-reperfusion injury-induced renal fibrosis mouse model (GSE197815) revealed increased chromatin accessibility in the promoter regions of POSTN, FSTL1, and FSCN1 genes during the progression of renal fibrosis." (PMID 40588562, 2025). "We aimed to evaluate periostin’s role as an indicator for detecting renal fibrosis in the early stages of DKD, alongside RRI and PSWE." (PMID 41316003, 2025). "Previous studies have shown that periostin promoted renal fibrosis through the p38 MAPK pathway after acute kidney injury triggered by hypoxia or ischemia‐reperfusion injury." (PMID 39570100, 2024). "In rodent models, therapeutics targeting periostin alone provided protection from chemically induced renal injury, diabetic nephropathy, or renal fibrosis, demonstrating an active role for periostin in kidney pathology." (PMID 37371758, 2023). "POSTN, a previously demonstrated signature protein for renal fibrosis, exhibited a 5-fold increase in obstructed kidneys." (PMID 36804530, 2023). "According to previous studies, overexpression of POSTN leads to cell proliferation and increased renal fibrosis, which finally leads to reduced renal function." (PMID 37130146, 2023). "This study aimed to evaluate the usefulness of vanin-1 and periostin in urine as markers of the autoimmune process in kidneys and renal fibrosis in IgA nephropathy (IgAN) and IgA vasculitis with nephritis (IgAVN)." (PMID 35268356, 2022). "Genetic or pharmacologic inhibition of periostin blocked the progression of renal fibrosis, providing a novel biomarker as well as target of therapy for chronic kidney disease." (PMID 35707463, 2022). "This study aimed to evaluate the significance of vanin-1 and periostin in urine for the autoimmune inflammatory process in kidneys and renal fibrosis in IgAN and IgAVN." (PMID 35268356, 2022). "AKI progression follows periostin expression and leads to renal fibrosis in response to hypoxia or ischemia." (PMID 35268356, 2022). "In conclusion, periostin seems to be a promising, non-invasive marker for assessing renal fibrosis in children with CON." (PMID 34768419, 2021). "Overexpression of periostin following renal injury was described in different models of renal fibrosis, such as UUO, 5/6 nephrectomy, hypertensive renal injury, and renal I-R injury." (PMID 34768419, 2021). "Periostin is mainly expressed in tubulointerstitial areas in renal fibrosis, and urinary periostin levels have been shown to be related with tubular damage." (PMID 34607314, 2021). "In our opinion, periostin seems to be a promising, non-invasive marker for the assessment of renal fibrosis in children with CON." (PMID 34768419, 2021). "Although we confirmed that periostin is strongly related to renal fibrosis, we still know too little about the regulation of periostin expression and its signaling pathways." (PMID 34768419, 2021). "Overexpression of periostin was reported in numerous experimental and clinical studies of renal fibrosis." (PMID 34768419, 2021).
renal fibrosis (continued). "Increased expression of periostin was positively related to the severity of renal fibrosis in the mouse model of bilateral kidney and unilateral ureteral obstruction." (PMID 34992536, 2021). "Recently, accumulation of periostin, an extracellular matrix protein, was shown to augment renal fibrosis." (PMID 28819200, 2017). "Interestingly, increased p300 in proximal tubular cells (PTCs) promoted renal fibrosis development by mediating the endothelial to mesenchymal transition (EndMT) via upregulation of the mesenchymal-transition-related secreted proteins POSTN, FSTL1, and FSCN1." (PMID 40588562, 2025). "Such experimental approach has been employed in the case of renal fibrosis where POSTN knockout in mice as well as POSTN blockade in mice normally expressing POSTN were both correlated with reduced levels of profibrotic markers after mechanical stress in vivo and in vitro." (PMID 37939043, 2023). "Preventing periostin-mediated renal fibrosis and inflammation might be a promising strategy for treating a hypertensive renal injury." (PMID 34084130, 2021). "In conclusion, the results of this study suggested that periostin acts as a key mediator of tubular fibrosis in DM patients, and treatment with the PA could be considered as a modality to prevent renal fibrosis under diabetic conditions." (PMID 28819200, 2017). "Thus, we evaluated the effect of periostin inhibition by an aptamer-based inhibitor on renal fibrosis under diabetic conditions." (PMID 28819200, 2017). "Seven days after unilateral ureteral obstruction (UUO) induced renal fibrosis, we found that ≈ 80% of Col1+ myofibroblasts, αSMA+ myofibroblasts, and POSTN+ myofibroblasts in fibrotic kidneys were ZsGreen+ (nonBM‐MSCs lineages), but not tdTomato+ (BM‐MSCs lineages)." (PMID 41309504, 2026). "After blocking the effect of Ang II, it can improve renal hemodynamics, reduce proteinuria and the expression of periostin in renal tissue, suggesting that periostin may be involved in the process of Ang II-induced renal fibrosis, but its specific mechanism remains to be studied." (PMID 33241962, 2020). "Periostin level, in conjunction with RRI and PSWE, serves as a novel and reliable markers of renal fibrosis." (PMID 41316003, 2025). "Given that both POSTN and SPP1/OPN are potent drivers of fibrosis, we investigated renal fibrosis 28d post-MI and found a significant increase." (PMID 41350805, 2025). "Periostin, RRI and PSWE provide valuable insight into the combined use of biochemical and imaging markers for early detection of renal fibrosis in DKD monitoring of DKD progression." (PMID 41316003, 2025). "The current study highlights the potential of periostin, in conjunction with RRI and PSWE, as a reliable multiparametric approach for the assessment of renal fibrosis in diabetic kidney disease (DKD)." (PMID 41316003, 2025). "Periostin and matrix metalloproteinase-2 (MMP-2) were selected to evaluate the effect of irisin on renal fibrosis in UUO mice." (PMID 38870184, 2024). "Therefore, periostin may serve as a biomarker of renal fibrosis in diabetic kidney disease." (PMID 39570100, 2024). "The aim of the study was to investigate the predictive value of urinary endoglin, periostin, cytokeratin-18, and transforming growth factor-β1 (TGF-β1) for assessing the severity of renal fibrosis in 81 children with CON and 60 controls." (PMID 34768419, 2021). "It is well-known that TGF-β1 is the major stimulator of endoglin and periostin expression, periostin creates a feedback loop with TGF-β1, and CK18 was identified as an important factor in renal fibrosis." (PMID 34768419, 2021). "The absence of POSTN in DN contributes to renal fibrosis alleviation by improving pancreatic β-cell function." (PMID 37845302, 2023). "Therefore, the aim of our study was to investigate the predictive value of urinary endoglin, periostin, CK-18, and TGF-β1 for assessing the severity of renal fibrosis in children with congenital obstructive nephropathy." (PMID 34768419, 2021).
renal fibrosis (continued). "Interestingly, renal fibrosis and inflammatory mediators, including TGF-β, angiotensin II, PDGF-B, and IL-4 and IL-13, could upregulate the expression of periostin." (PMID 34992536, 2021). "Based on our demonstration that p300 promotes the secretion of POSTN, FSTL1, and FSCN1 in renal proximal tubule cells, thereby increasing the EndMT, we next investigated whether selective inhibition of p300 suppressed the secretion of these three proteins in a UUO-induced renal fibrosis mouse model." (PMID 40588562, 2025).
chronic rhinosinusitis (23 papers, 2015 to 2026). Chronic form of sinusitis. "As eoshinophilic chronic rhinosinusitis has a higher incident rate, studies show that periostin has participated in the process of inflammation and remodeling." (PMID 32954441, 2021). "Osteopontin together with periostin, has been shown to mediate chronic rhinosinusitis inflammation by inducing a proliferative response of the ECM99." (PMID 28584245, 2017). "Periostin is a new marker with special expression in chronic rhinosinusitis." (PMID 37046572, 2023). "The use of isoforms specific for chronic rhinosinusitis, as well as the standardization of assay methods, may enable an objective determination of the clinical usefulness of periostin as a CRS marker." (PMID 37046572, 2023). "In addition, periostin production is affected by several complications, including allergic rhinitis, chronic rhinosinusitis, AD, and aspirin intolerance." (PMID 34439751, 2021). "In previous studies, the serum periostin level had potential as a single biomarker to predict eosinophilic airway inflammation and risk of a decline in FEV1 in asthmatic patients and was associated with late onset, high eosinophil counts, AERD, and chronic sinusitis." (PMID 30473714, 2018). "Our results confirmed that high serum periostin levels were correlated with late onset and high peripheral blood eosinophil counts, but demonstrated that high serum periostin levels were not correlated with AERD and chronic sinusitis." (PMID 30473714, 2018).
idiopathic pulmonary fibrosis (23 papers, 2013 to 2025). Idiopathic pulmonary fibrosis (IPF) is a nonneoplastic pulmonary disease that is characterized by the formation of scar tissue within the lungs in the absence of any known cause. "Serum monomeric and total periostin were higher in patients with RA-ILD with definite usual interstitial pneumonia pattern compared with other ILD patterns." (PMID 38002712, 2023). "Idiopathic pulmonary fibrosis (IPF) patients' lung fibroblasts expressed periostin 3.5 times more than normal lung fibroblasts." (PMID 36224629, 2022). "Periostin induces cell proliferation via integrin binding and is essential in fibrotic diseases such as idiopathic pulmonary fibrosis (IPF)." (PMID 39403603, 2024).